MMP11 (matrix metallopeptidase 11)
Diseases named in the same sentence as MMP11 in open-access papers (continued):
Sharing a sentence is not in itself a finding about the gene and the disease.
cancer (continued). "Pathway enrichment analysis further demonstrated that MMP11(+) F01 cells exhibited activation of pro-tumorigenic and immunosuppressive pathways (IL-2, angiogenesis, PI3K-AKT-mTOR, and TGFβ), while MMP11(−) F01 cells enriched anti-cancer and immunostimulatory pathways (IFN-α/γ)." (PMID 40607407, 2025). "However, the downregulation of ADAMTS2, ADAMTS14, MMP11, and MMP7, metalloproteases that help in cancer cell invasiveness by dissolving the ECM components, could prevent cancer invasive potential." (PMID 37834191, 2023). "The other 6 putative CPAs demonstrated diverse expression profiles, ranging from those found only in a restricted set of cancer types (IGF2BP3, ADAM12), to those overexpressed in most cancer types but also demonstrating elevated expression in normal female reproductive tissues (CAPN6, MMP11)." (PMID 33087697, 2020). "Specifically, CTD-2218G20.2 was predicted to interact with 86 proteins (Pearson correlation coefficient, PCC > 0.3), some of which, including PSG4, PSG5, and PSG7, could also interact with cancer-related proteins, including KISS1, TIMP2, MMP11, IGFBP1, EGFR, and CDKN1C." (PMID 32117443, 2020). "This study confirms that mRNA for CXCR2, VEGF-A, MMP11 and TGF-β mRNA's are all significantly increased after exposure to volatile anaesthetics, indicating the activation of key molecular mediators of metastasis such as cancer cell transformation, basement membrane degradation and angiogenesis." (PMID 27028996, 2016). "VEGF, TRAILR2, MMP2 and MMP11 were not regulated by the cancer cell conditioned medium." (PMID 26362269, 2015). "In addition, it has been proposed that, although in tumorigenesis induced by MMP-11 cancer cell proliferation was not increased, cancer cell death through apoptosis and necrosis was decreased, indicating that the function of MMP-11 is to promote cancer cell survival in the stromal environment." (PMID 37108185, 2023). "Although in vitro models (cancer cells/adipocytes) confirmed that phenotype of CAAs may be triggered directly by cancer cells, and some candidate molecules released by tumor cells such as TNF-α, Wnt3a, Wnt5a, and MMP11 have been proposed, the exact mechanism remains elusive." (PMID 33916703, 2021). "None of the six genes (MMP11, ANGPTL1, GSTM5, IQGAP3, UHRF1, and CCBE1) have previously been categorized as carcinoma biomarkers collectively." (PMID 39596491, 2024). "It has been found that stromelysin-3 (MMP-11), a member of the MMP family that acts as a survival factor on cancer cells rather than as an inducer of cancer cell proliferation, is mainly involved in the formation of tumors rather than the growth of them." (PMID 38007463, 2023). "Proteases present in malignant tumours but not in normal skin included: PGC, BAP1, caspase-8, F13A1, MMP11, MMP23, MMP25, MMP26 and granzyme-A." (PMID 35327667, 2022). "Unlike many other MMPs, MMP-11 does not degrade major extracellular matrix components, but instead targets specific substrates, notably the insulin-like growth factor-binding protein-I (IGFBP-I) suggesting a unique role in cancer progression." (PMID 38438841, 2024). "If serum detection is achievable, ubiquitously upregulated MMPs such as MMP11 or MMP13 could serve as a pan-cancer marker, capable of identifying the presence of cancer but not the specific location of the cancer." (PMID 31200666, 2019).
infection (6 papers, 2015 to 2025). The state of being infected such as from the introduction of a foreign agent such as serum, vaccine, antigenic substance or organism. "Likewise, matrix metallopeptidase 1 (MMP1), MMP2, and MMP14 were significantly up-regulated while the transcript of MMP11 was repressed by infection." (PMID 27197554, 2016). "However, our screening also identified invasion- and migration-related genes that were not significantly modulated upon infection (i.e., PAPPA, SNAIL, MMP9, MMP11, ICAM1, CTNNB1, and CDH2)." (PMID 41450565, 2025).
metabolic disorders (1 paper, 2020). "Other genes commonly dysregulated in both SO diets linked to metabolic disorders include Cartpt, Hcrt, Mmp11, and Abhd8 (all upregulated)." (PMID 31912136, 2020).
MMP11 also shares sentences with these, for which no sentence is quoted: non-small cell lung carcinoma (5 papers); stomach cancer (3); adenocarcinoma (2); atherosclerosis (2); dermatofibroma (2); leukemia (2); liver failure (2); Sepsis (2); acute respiratory distress syndrome (1); and neck tumors (1); Arthritis (1); astrocytic tumor (1); benign fibrous histiocytoma (1); benign tumors (1); bladder urothelial carcinoma (1); breast ductal carcinoma (1); cervical carcinoma (1); cervical tumor (1); clear cell renal carcinoma (1); conjunctiva (1); connective tissue disorder (1); desmoid tumor (1); diabetic retinopathy (1); endometrioid endometrial carcinomas (1); endometrioid ovarian cancer (1); epithelial ovarian tumors (1); esophageal adenocarcinoma (1); Glucose intolerance (1); Hepatitis (1); Infertility (1).
A further 18 diseases each share a sentence with MMP11 in 1 paper.